CCND1 (cyclin D1)
Diseases named in the same sentence as CCND1 in open-access papers (continued):
Sharing a sentence is not in itself a finding about the gene and the disease.
breast cancer (continued). "A recent study showed that ecto-5′-nucleotidase (CD73) could promote the proliferation of breast cancer cells and breast cells in vitro through the AKT/glycogen synthase kinase-3β (GSK-3β)/β-catenin/cyclin D1 signaling pathway." (PMID 35910774, 2022). "In addition, western blotting indicated that miR-885-3p suppressed the progression of breast cancer cells by downregulating the expression level of PCNA and the expression levels of CDK2/CCNE1 and CDK4/6/CCND1 (Student’s t test, p < 0.05)." (PMID 35383130, 2022). "Cyclin D1 and CDK4 play particularly important roles in mammary gland biology and breast cancer." (PMID 35248122, 2022). "For example, cyclin D1 is required for mammary epithelial proliferation in pregnancy, and knockout of either cyclin D1 or CDK4 prevents the development of mammary carcinomas from luminal epithelial cells driven by particular oncogenes, such as Neu or Ras, in mice." (PMID 35248122, 2022). "Furthermore, 9-cis RA decreased cyclin D1 and D3 expression levels as well as the expression and activity of CDK2 and CDK4 in breast cancer cells." (PMID 34444715, 2021). "In addition, four genes CCND1, ESR1, STAT3, and NCOA1 were enriched for mammary neoplasms, experimental (C0024668)." (PMID 34504716, 2021). "As breast cancer biopsies were sequenced, it became apparent that a significant proportion of patient samples exhibited dysregulation of the CDK4/cyclin D1/Rb interaction with overexpression/amplification of cyclin D1 (CCND1) and alterations in p16." (PMID 34771508, 2021). "Gene amplification is the most frequent genetic alteration in breast cancer with MYC, CCND1, epidermal growth factor receptor (EGFR), fibroblast growth factor receptor (FGFR), CDK4, and MDM2 being the genes most frequently amplified in primary and recurrent breast tumors." (PMID 33996588, 2021). "Akt1, but not Akt2, was shown to promote breast cancer cell proliferation by upregulating cyclin D1 and S6 (a downstream target of mTORC1) in IBH-6 and T47D breast cancer cells." (PMID 34298660, 2021). "Three genes CCND1, ESR1, and STAT3 were enriched for mammary neoplasms, experimental (C0024668)." (PMID 34504716, 2021). "In breast cancer, NUDT5 overexpression not only increases ATP synthesis and reconstructs tumor cell chromosomes, it also activates the AKT pathways and increases the expression of Cyclin D1, which promotes cancer cell resistance to ER-targeting drugs." (PMID 33571243, 2021). "For example, circHMCU modulates breast cancer cell proliferation and mesenchymal characteristics by sponging let-7 miRNAs and, subsequently, activates let-7 targeted genes, including HMGA2, c-myc and CCND1." (PMID 34572067, 2021). "Dimethyl melaleucate and three structurally related PTs, ursolic acid, 18α-glycyrrhetinic acid, and carbenoxolone suppress EGF mediated breast cancer proliferation through sustained inhibition of EGFR and its downstream effectors STAT3 and cyclin D1 in breast cancer lines." (PMID 34681605, 2021). "In addition, the knockdown of NUDT5 suppressed breast cancer cell lines proliferation, migration and invasion, and dramatically inhibited the AKT phosphorylation at Thr308 and expression of Cyclin D1." (PMID 33571243, 2021). "For instance, cyclin D1 is upregulated in a subgroup of patients with luminal breast cancer who do not respond to endocrine treatment." (PMID 34282517, 2021).
breast cancer (continued). "Both miR-15 and miR-16 are considered as tumor suppressors that could be used for therapy of inhibiting BCL2-, CCND1-, and CCND2-overexpressing tumors, e.g., chronic lymphocytic leukemia, breast cancer, prostate, and lung cancer." (PMID 33788050, 2021). "However, a monoterpenoid β-thujaplicin induces G0/G1 phase arrest and regulates cyclin D1, cyclin E, and CDK4, thereby preventing the ER-basal-like MCF10DCIS.com human breast cancer cell proliferation." (PMID 34361615, 2021). "Various studies confirm changes in the expression of these genes or proteins upon bisphenol exposure: in breast cancer cell lines, low concentrations of BPAF and tetrachloro-BPA enhanced protein expression of c-Myc and cyclin D1, important for cell cycle progression." (PMID 34858639, 2021). "CNAs in CCND1, FGF3, FGF4, and FGF19, which are all located in the q-arm of chromosome 11 were more likely to be detected from patients with HR+/HER2+ and HR+/HER2− breast cancer (P < 0.001)." (PMID 32695676, 2020). "Moreover, downregulation of PIWIL2 decreased proliferation and survival of breast cancer stem cells through a decrease in the protein levels of STAT3, BCL-XL and Cyclin D1." (PMID 32357464, 2020). "In parallel, there was a significant increase in the expression of cyclin D1 in human and mouse breast cancer cells, but not in melanoma cells cultured in pericyte‐conditioned media." (PMID 32534480, 2020). "Moreover, it reveals the novel mechanism of DILA1 in regulating Cyclin D1 protein stability and suggests DILA1 is a specific therapeutic target to downregulate Cyclin D1 protein and reverse tamoxifen resistance in treating breast cancer." (PMID 33139730, 2020). "Together with similar Cyclin D1 mRNA levels in MCF7-Re and MCF7-Pa cells, these results suggest that protein degradation but not protein synthesis was responsible for the upregulated Cyclin D1 protein in tamoxifen-resistant breast cancer cells." (PMID 33139730, 2020). "Mice lacking cyclin D1 were also resistant to breast cancers induced by the erbB-2 and ras oncogenes, but were sensitive to breast cancers induced by other oncogenes like c-myc or Wnt-1." (PMID 31884567, 2020). "Furthermore, downregulation of MAC30 expression inactivated β-catenin, survivin, and cyclin D1 via suppression of Wnt/β-catenin and PI3K/Akt signaling pathways which affected the invasion and EMT of breast cancer MCF-7 and MDA-MB-231 cells." (PMID 32904598, 2020). "Previously, BS-181 was reported to induce G1-arrest and apoptosis, resulting from the down-regulation of G1 cyclin (cyclin D1) and anti-apoptotic proteins (MCL-1 and XIAP) in breast cancer cells and down-regulation of cyclin D1 and XIAP in gastric cancer cells." (PMID 33352782, 2020). "SEN2 had no results, while CCND1 is only known to be associated with non-AAC cancers such as oral cancer, esophageal cancer, breast cancer, and laryngeal cancer." (PMID 32483162, 2020). "In human breast cancer, PIN1 promotes oncogenesis via the cyclin D1 regulation." (PMID 32258027, 2020). "Among these markers, the role of cyclin D1 and p16 expression as prognostic markers for CDK4/6 inhibitors is still controversial, even in similar groups of patients with ER+/HER2- breast cancer, and requires further evaluation in preclinical and clinical models." (PMID 32899250, 2020). "Pin1 participates in a variety of processes, including cell proliferation, growth suppressor evasion, genome instability and centrosome amplification, and Pin1 acts on its substrates cyclin D1, AKT, ERα, β-catenin, NF-κB, and c-MYC at the tumour initiation stage in breast cancer." (PMID 32010480, 2020). "Qu firstly reported that downregulated MAC30 expression inhibited the breast cancer cell invasion and epithelial–mesenchymal transition (EMT) by suppressing Akt phosphorylation, β-catenin, survivin, and cyclin D1 in PI3K/Akt and Wnt/β-catenin signaling pathways." (PMID 32904598, 2020).
breast cancer (continued). "To confirm that miR-20b-5p regulated CCND1 and E2F1 expression, we performed three experiments, namely, a comparison between BCSCs and the control breast cancer cells, a dual-luciferase assay and western blot analysis after overexpression or knockdown of miR-20b-5p." (PMID 33008330, 2020). "The induction of breast cancer cell lines (MDA-MB-231 and T47D) with the TLR3 ligand induces cellular proliferation through an MyD88-dependent manner via induction of proinflammatory cytokine IL-6 and cyclin D1." (PMID 33072559, 2020). "Comparison of CCND1 amplification in 10,606 patients from the TCGA database and 10,109 patients from the MSKCC database revealed that ESCA and breast carcinoma had the highest incidence in the TCGA patients at 34.78% (64/184) and MSKCC patients at 18.55% (228/1,229) databases, respectively." (PMID 32903763, 2020). "The reduced expression levels of anti-apoptotic proteins, Bcl2 and Stat3, plus cell cycle regulator protein, Cyclin D1, using Real-Time PCR confirm that the C-PC-induced death of MCF-7 human breast cancer cells occurred through the mitochondrial pathway of apoptosis." (PMID 31263160, 2019). "In addition, Tnfaip8l2 prevented the EMT phenotype, by inhibiting the expression of β-catenin, cyclin D1 and c-Myc in MDA-MB-231 and MCF-7 breast cancer cells." (PMID 30700756, 2019). "Increased expression of either cyclin D1 or G9a was not significantly correlated with poor outcome breast cancer." (PMID 30718920, 2019). "The Spearman correlation analysis demonstrated a negative correlation between LINC01355 and CCND1 expression in breast cancer tissues (r = −0.3018, P = 0.0393)." (PMID 31243265, 2019). "Binding of transcription factors NF-κB and STAT3 to promoters of key proliferative genes such as cyclin D1 and c-Myc, in combination with ERα, provided the basis for estradiol-independent, non-canonical proliferation of ER+ breast cancer cells." (PMID 30736340, 2019). "It has been shown that CCND1 and MHC-I molecules are negatively correlated in breast cancer, suggesting CCND1 may modulate the presentation of peptide antigens, thereby affecting T cell activation." (PMID 31023256, 2019). "Five genes (MMP3, CDKN1A, RUNX1, TIMP2, CCND1) are common in cervical, ovarian, endometrial cancers, but not in breast cancer." (PMID 31205821, 2019). "Finally, we observed that knocking down Vimentin suppressed p-PI3K, p-AKT, c-JUN, c-Myc, and Cyclin D1(CCND1), N-cadherin and restored E-cadherin expression in MAP2K4-overexpressed breast cancer cells." (PMID 31761784, 2019). "In contrast to our result, Akt1 but not Akt2 was found to modulate the expression of Cyclin D1 in lung and breast cancer cells." (PMID 31252679, 2019). "First, ER+/LN−/HER2−, luminal A and B breast cancer patients with a CCND1-amplified tumour show worse 15-year BCSS relative to non-amplified patients." (PMID 30819233, 2019). "Cyclin D1 (CCND1) is a regulatory cofactor of CDK4/6, and is overexpressed in breast cancer." (PMID 31023256, 2019). "In addition, we found a significant inverse correlation between CCND1/E1 and SALL2 expression in various cancers, but most notoriously between CCNE1 and SALL2 in breast cancer." (PMID 29689621, 2018). "The molecular mechanism behind SNP rs992531 and poor breast cancer outcome in ER-positive cases may therefore involve altered RHOBTB2 expression and its interplay with cyclin D1 and the oestrogen receptor." (PMID 29423119, 2018). "The reduction in migration could be related to the fact that we found ID4 associated with CCND1, which regulates migration and proliferation in breast cancer cells; perhaps, these changes in migration are due to an interaction between ID4 and CCND1." (PMID 30139383, 2018). "When mice harboring mammary tumors overexpressing the ERBB2 gene were crossed with CDK4 knockout mice, the resulting littermates did not develop tumors, and the acute loss of cyclin D1 or CDK4 proteins mediated via RNA interference attenuated tumor growth." (PMID 30443290, 2018).
breast cancer (continued). "Depletion of P-Rex1 from breast cancer cells failed to affect cell cycle progression, cyclin D1 induction, Akt activation and apoptotic responses." (PMID 29983884, 2018). "In 2014, the Cyclin D1 (CCND1) A870G GG genotype was found to be infrequent in Taiwanese TNBC patients, which may contribute to distinguishing the TNBC patients from other breast cancer patients." (PMID 30096175, 2018). "These cells showed no change in the levels of proteins involved in breast cancer–related signaling pathways or β-catenin-dependent pathways, such as ER, β-catenin, and cyclin D1." (PMID 29765514, 2018). "Altogether, our findings suggest that miR-34a is an MDR and prognosis indicator of breast cancer, which may participate in the regulation of drug-resistant breast cancer by targeting BCL-2, CCND1, and NOTCH1." (PMID 29290947, 2017). "The mechanisms governing the induction of cyclin D1 in the stroma of breast cancer patients is not known." (PMID 29137220, 2017). "In other words, miR-34a may participate in the regulation of multidrug resistance in breast cancer by down-regulating the expression of BCL-2, CCND1 and NOTCH1." (PMID 29290947, 2017). "Previous publications did not report the presence of cyclin D1 protein in breast cancer stroma but focused on reporting the more abundant of cyclin D1 in cancer epithelial cells." (PMID 29137220, 2017). "Our method identified not only many known cancer genes such as CCND1, MYC, ERBB2, RB1 and BRCA1 in breast cancer but also many novel protein‐coding genes as well as non‐coding RNAs that may contribute to carcinogenesis." (PMID 28719033, 2017). "MiR-34a may participate in the regulation of drug-resistant breast cancer by targeting BCL-2, CCND1, and NOTCH1." (PMID 29290947, 2017). "Of the breast cancers assessed, there were gains in HER-2 in 33%, CCND1 in 32%, and C-MYC in 39%." (PMID 28697743, 2017). "In HER2-driven or oncogenic HRAS-driven breast cancer in mice, tumor development was specifically protected by depleting cyclin D1 or CDK4 or expressing the CDK4- or CDK6-specific inhibitor INK4A or a dominant-negative mutant form of K112E cyclin D1." (PMID 28474232, 2017). "This indicated that miR-34a is involved in the regulation of drug-resistant breast cancer and may target BCL-2, CCND1, and NOTCH1." (PMID 29290947, 2017). "Immunohistochemical nuclear expression of cyclin D1 (n = 364) and amplification of the gene CCND1 by fluorescent in situ hybridization (n = 255) was performed on tissue microarray sections from patients with T1-2N0M0 breast cancer." (PMID 28528450, 2017). "The expression of cyclin D1 was not significantly different in breast cancer patients with various hormone receptor groups." (PMID 28533512, 2017). "Cyclin D1 expression and CCND1 amplification in breast cancer subtypes." (PMID 29140993, 2017). "Cyclin D1/CDK4 complexes interact and phosphorylate the scaffold protein filamin A, a member of the actin-binding protein family, thereby controlling the invasion potential of breast cancer cells." (PMID 29066743, 2017). "Moreover, cyclin D1 is one of the ER transcriptional targets, thus rationalizing the use of CDK4/6 inhibitors in ERα+ breast cancer." (PMID 28454587, 2017). "In an experiment on 7,12-dimethylbenz[a]anthracene (DMBA) induced breast cancer in FNB/N type rats, it was revealed that DMBA resulted in higher expression of the genes involved in carcinogenesis, including c-myc and cyclin-D1, as well as activation of the NF-kB pathway." (PMID 28702133, 2017). "In breast cancer EYA1 levels are increased, which promotes proliferation by activating cyclin D1." (PMID 29285235, 2017). "In addition, a high correlation was observed between copy number and gene expression in regions commonly amplified in breast cancer, such as 20q13 (B-MYB), 17q (HER-2) and 11q (CCND1)." (PMID 28697743, 2017).
breast cancer (continued). "Furthermore, NOTCH1 has been identified as a mediator of the RAS oncogenic pathway; this is often deregulated during the early stages of breast cancers and participates in the JAG1/NOTCH1/CCND1 axis critical for maintaining proliferation of TN BC cells." (PMID 27888801, 2017). "CCND1, a protein related to cell cycle, was demonstrated to be involved in above EGFR-mediated G1/S transition,which contributed to the multidrug resistance in breast cancer cells." (PMID 29290947, 2017). "We found that ectopic expression of ALX4 could inhibit the canonical Wnt signaling activity in breast cancer by TOP/FOP flash reporter assay and the Wnt target functional genes MMP7, c-Myc and Cyclin D1 were down regulated both at protein and mRNA level." (PMID 29183346, 2017). "CCND1 amplification had no significant prognostic impact on breast cancer mortality in all cases together (OR 1.4, 95% CI 0.4–4.4, p value 0.56) or in ER-positive and ER-negative cases separately (data not shown)." (PMID 28528450, 2017). "Copy number aberrations (CNAs) in known breast cancer driver genes present in the PDTXs included gains/amplifications of MYC (78%), CCNE1 (34%), ZNF703 (25%), CCND1 (31%), MDM2 (25%), and ERBB2 (9%) and deletions of PTEN (41%), PPP2R2A (72%), CDKN2A (47%), and CDKN2B (47%)." (PMID 27641504, 2016). "This confirms the strong effect of PAC on ERα in ERα− breast cancer cells and indicates that this gene as well as its targets c-MYC and CCND1 might play important roles in the response of these cells to PAC." (PMID 27465411, 2016). "For the other top-ranked miRNAs, five have no validated targets but have many predicted targets related to breast cancer such as AKT, AKT1, CCND1, EGFR1, ERBB2, SRC, PTEN which have been used as breast cancer biomarkers for prognosis, diagnosis, drug efficacy, and disease progression." (PMID 27833082, 2016). "Furthermore, NLN and CCND1, PLAU, and SEPN1 were directly targeted by miR-193a-5p and miR-193a-3p, respectively, in breast cancer cells." (PMID 27307030, 2016). "Since lower concentrations of NO reduced proliferation of AA breast cancer cell lines, we further examined its effect on Mn SOD and Cu/Zn SOD as well as on various proliferation (cyclin D1 and PCNA), apoptosis (Bax and Bcl2), and oxidative stress (NOX4) markers." (PMID 27473585, 2016). "Moreover, anti-miR-550a-3p had a smaller effect on cyclin D1 and c-myc in MDA-MB-231 cells, which have the lowest level of endogenous miR-550a-3p among the sampled breast cancer cell lines." (PMID 27462780, 2016). "ER's target genes, PGR and CCND1 were also overexpressed in MALAT1 altered group, indicating MALAT1 might play a role the regulation of ER expression in breast cancer." (PMID 27191888, 2016). "Meanwhile, PIAS3 increased cyclin D1 expression in MCF-7 and T47D cells but inhibited the same in MDA-MB-231 and SKBR3 cells, suggesting that different effects of PIAS3 on breast cancer cells may be modulated by ER." (PMID 26768588, 2016). "In addition, cell viability was evaluated after inhibition of cyclin D1 expression by small-molecule inhibitors 4-CPA or CyP, which have been demonstrated to inhibit CCND1 promoter activity and breast cancer cell growth." (PMID 27129163, 2016). "CCND1 is frequently amplified/overexpressed in human cancers, and BCL3 is a candidate proto-oncogene whose function is reportedly required for metastasis of HER2-positive breast cancer cells." (PMID 27382434, 2016).